HES1 (hes family bHLH transcription factor 1)
Diseases named in the same sentence as HES1 in open-access papers (continued):
Sharing a sentence is not in itself a finding about the gene and the disease.
tumor (continued). "DAPT treatment suppressed tumor growth, decreased HES1 expression and the level of NICD, and also led to the enhancement of apoptosis and reduction in cell proliferation in vivo." (PMID 33673088, 2021). "HES1 downregulation decreased BCSCs-derived tumor size and weight and the effects were restored by Slug overexpression in xenograft models with the limiting dilution of 1.0 × 105 cells per mouse." (PMID 33390847, 2021). "In this study, we proved that EERAC remarkably inhibited CRC through suppressing Notch/DLL4/Hes1 pathway, and further inhibited tumor angiogenesis." (PMID 34476005, 2021). "Treating mice bearing pancreatic cancer xenografts with PF-03084014 (150 mg/kg), alone or combined with gemcitabine, downregulated NICD Hey-1 and Hes-1, resulted in tumor regression, and reduced cancer stem cells." (PMID 33673088, 2021). "Tumor tissue has increased mRNA expression of Notch2, and downstream mediators hairy ears, Y-linked (HEY), and hairy and enhancer of split 1 (HES1) compared to normal bone." (PMID 34660770, 2021). "Consistent with in vitro results, transplantations of BCSC populations with limiting dilution assay revealed that the tumor formation probability was severely reduced upon HES1 knockdown and almost rescued by Slug overexpression." (PMID 33390847, 2021). "Among these signaling pathways, Notch1/Hes1 which plays a crucial role in tumor development can be activated by EIF5A2." (PMID 33726845, 2021). "In contrast, HES1 over-expression weakened the effects of miR-126b, as evidenced by suppressed tumor growth and enhanced cell apoptosis in OS." (PMID 32972441, 2020). "To accurately assess the nuclear expression of HES-1 in tumor cells via IHC, we selected regions only composed of tumor cell nests and analyzed them using digital image analysis." (PMID 32974155, 2020). "Nonetheless, we cannot exclude additional, direct effects of MMP13 and the other Notch targets on tumor cells, as we showed positive immunoreactivity for HES1, DLL4, and MMP13 proteins in iCCA cells." (PMID 32042099, 2020). "The aim was to analyse the tumor expression of Notch1, Hes1, Ascl1, and DLL3in Small-Cell Lung Cancer (SCLC) and each such biomarker’s potentialassociation with clinical characteristics and prognosis afterplatinum-doublet chemotherapy (PDCT)." (PMID 33104707, 2020). "Particularly, previous investigations indicated that NOTCH1 and its target gene HES1 were markedly increased in GSCs, leading to tumor invasion and recurrence of GBM, and Notch1 overexpression was also associated with low overall survival." (PMID 32526957, 2020). "Weekly dosing of AL101 led to continuous Notch inhibition (as measured by Notch-regulated HES1 mRNA) and clinical activity against several tumour types." (PMID 32575680, 2020). "We analyzed HES1 protein expression in tumor sections by immunohistochemistry to confirm these observations and to determine the spatial distribution and proliferative state of HES1+ cells." (PMID 31863004, 2019). "In contrast to Hes1, the transcription factor Myod1 identified a subset of tumor cells that remained proliferative after vismodegib treatment." (PMID 31863004, 2019). "As2O3 disturbed the morphological development of tumor vessels and downregulated the protein levels of delta-like canonical Notch ligand 4 (Dll4), Notch1, and Hes1 in vivo." (PMID 31093499, 2019). "We confirmed that GFP+ cells expressed high levels of GFP, Notch1, Nrarp, Hes1 and Olfm4, the three-latter representing direct Notch targets, indicating that the Notch pathway is indeed active in Notch1+ tumour cells." (PMID 30696875, 2019). "We determined the protein level of the Notch pathway-related factors in tumor tissues and found that As2O3 reduced the protein levels of Dll4, Notch1, and Hes1 in vivo." (PMID 31093499, 2019).
tumor (continued). "Studies have shown that Hes1, a downstream effector of the Notch signaling, is closely involved in cancer progression, chemoresistance, promotes self-renewal and tumor initiation in various cancers." (PMID 31470883, 2019). "HES1 knockdown inhibited tumor growth, as determined by our results pertaining to xenograft tumor size and tumor wet weight, in xenografts comprising cells transfected with siRNA425 and siRNA670 compared with xenografts comprising control cells." (PMID 29665790, 2018). "In fact, the targeted deletion of JAGGED1 in LGR5+ tumor-initiating cells resulted in the silencing of HES1 expression, the disruption of the stem cell niche and a dramatic reduction in the proliferative activity of APC-deficient intestinal tumors in vivo." (PMID 29652830, 2018). "The correlation between aberrant activation of NOTCH/HES1 stemness signaling and tumor metastases has been revealed through a series of experimental investigations." (PMID 30180881, 2018). "Relative mRNA expression of NOTCH1 and 3 and HES1 mRNA was significantly lower in tumor compared with in normal tissue." (PMID 29533972, 2018). "All genes, except HES1, are significantly modified in their expression levels in tumor compared to normal tissues (p < 0.001)." (PMID 30380753, 2018). "The statistical proliferative index of tumor tissues stained for Ki67 came to the conclusion that HES1 knockdown also affected cell proliferation in vivo." (PMID 29665790, 2018). "Several evidence reported that in vivo hypoxia upregulated expression of Dll4, Jagged1, Notch1, Notch4, Hes1, and Hey which in turn promoted tumor angiogenesis." (PMID 28157712, 2017). "JAG1, JAG2, HEY1 and HES1 had relatively higher expression in tumor samples compared to the pool of normal controls." (PMID 28146432, 2017). "Blockade of the effector gene Hes1 by miR199b-5p inhibits proliferation of cancer cells and reduces tumor stem-cell populations." (PMID 28881855, 2017). "Increased miR‐182 represses HES1, a key player in the Notch signaling pathway that also acts as a tumor suppressor in MTC." (PMID 28122586, 2017). "Dll1 and Dll3 seemed less expressed in the tumor epithelium, and Dll4, all Notch receptors, and Hes1 seemed upregulated." (PMID 28086833, 2017). "The expression of JAGGED1 and HES1 was also determined in samples in which sufficient RNA was available and variable levels of expression were quantified independently of tumor type." (PMID 28915655, 2017). "Since our studies revealed Hes-1 as one of most deregulated genes in ATL SP cells and NOTCH1 signaling has been implicated in ATL tumor growth in vitro and in vivo, we next investigated the role of NOTCH1 signaling in SP cells maintenance." (PMID 28920078, 2017). "The expression of TNF-α and Hes1 (a downstream effector of Notch signaling) in tumor tissue was higher than both normal muscle and atrophic muscle, while the expression of Klotho [an anti-inflammatory factor] was lower." (PMID 27378829, 2016). "In contrast, progenitor genes, such as Rbpj and Hes1 (hes family bHLH transcription factor 1) as well as Bmi1 and Ring1b were re-expressed in 3D-ADMs and tumor cells." (PMID 26716510, 2016). "Jagged1 and ICN1 were normally expressed in cytoplasm of tumor cell, while Hes1 was stained on tumor nuclear site." (PMID 27612417, 2016). "Reduced levels of NICD1 and Notch1 target genes, such as Skp2, c-Myc and Hes1, confirmed that PF-03084014 efficiently reached the target in Ptenpc−/− tumours." (PMID 27941799, 2016). "Nearly 80% of the HCC patients also exhibited higher expression levels of Hes1 in the tumor tissues." (PMID 25668819, 2015). "A significant upregulation of protein levels of Notch1 and Notch2 receptors, and Hes1 and Hey1 products was observed in bortezomib-treated group when compared with tumor alone group." (PMID 26431276, 2015).
tumor (continued). "In contrast, an average of 61.4 ± 46.7 metastatic tumor nodules were detected on lung surface in seven of eight mice inoculated with Hes1-expressing cells based on histological examination." (PMID 26452025, 2015). "The Notch3 and Hes1 gene expression levels were significantly increased in the tumor tissue compared with the normal liver tissue from the same patient." (PMID 25668819, 2015). "We show that bortezomib administration to naïve or tumor-bearing mice upregulates mRNA expression of Hes1 and Hey1 and their protein products." (PMID 26431276, 2015). "Inhibition of Hes1 in APCMin mice has decreased tumor cell proliferation and has led to tumor cell differentiation into intestinal epithelial cells." (PMID 26650241, 2015). "Then, E4-ECsScr and E4-ECsJag1KD were co-cultured with MDA-231 cells and the expression of canonical notch downstream target genes Hes1 and Hey1 was determined in tumor cells after sorting." (PMID 25380486, 2014). "Mechanistically we demonstrate that the activity of KPT-185 is associated with nuclear retention of Fbw7; which degrades nuclear Notch-1 leading to decreased tumor promoting markers such as C-Myc, Cyclin-D1, Hes1 and VEGF." (PMID 24899509, 2014). "HES1 has been suggested to have both oncogenic and tumor suppressive functions, whereas KLF10 has been suggested to be a tumor suppressor gene." (PMID 24885297, 2014). "Notch3, Jagged1, Delta1 and the downstream effector gene, hairy and enhancer of split 1 (Hes1), are highly expressed in the HepG2 tumor cell line, which was thought to be necessary for malignant liver cell proliferation." (PMID 24919811, 2014). "Nuclear HES1 was seen to be increased in CYLD defective tumours, but the difference from control epidermis was smaller than for LEF1 and RUNX1 (p = 0.027)." (PMID 25565632, 2014). "HES1 mRNA expression was elevated in tumor samples relative to normal bone, but decreased in tumor samples from dogs with a DFI < 100 days relative to those with a DFI > 300 days." (PMID 23816051, 2013). "al. found that interactions with HES1 stimulates PARP1 activation and cleavage, ultimately resulting in apoptosis in B-ALL (overall a tumor suppressor role for HES1)." (PMID 23816051, 2013). "Notch/HES1 has also been shown to have tumor suppressor activity in some cancers including hepatocellular carcinoma, B-cell ALL, myeloid leukemia and neuroblastoma." (PMID 23816051, 2013). "The second one, exemplified by female V015, showed strong and widely distributed Hes1 expression, relatively high estrogen receptor expression and undetectable p63 expression in the tumor." (PMID 23826634, 2013). "The thymi of the Tcf1+/− control mouse and the two Tcf1−/− tumor mice displaying high Wnt activity were further examined for the RNA expression levels of Lef1 and Hes1." (PMID 23185135, 2012). "We observed a significant reduction in HES1 mRNA and protein in the tumor xenografts treated with NP-siDCAMKL-1, DAPT, and NP-siDCAMKL-1+DAPT compared to control or NP-siSCR treated tumors." (PMID 21929751, 2011). "The universal Hh target Gli1 is expressed in Ptc1 deleted tumours as well as in those with additional loss of RBP-J, as is Hes1, a target of both the Hh and Notch pathways." (PMID 20950430, 2010). "Here, we envisage the use and delivery of miR199b-5p in situ into the cerebellum of MB-affected children under 3 years of age (and positive to HES1), to thus impair the maintenance of the tumor-initiating CD133+ cancer cells." (PMID 19308264, 2009). "This notion is further reaffirmed by data obtained from a limited analysis of gene expression in Hes1 transgenic tumor samples, showing expression of a combination of different Notch targets at varying levels in different tumors." (PMID 19688092, 2009). "Therefore, Hes1 promotes tumor cell proliferation by driving the cell cycle progression and enhances tumor cell viability by inhibiting tumor cell senescence and apoptosis." (PMID 40755759, 2025).
tumor (continued). "Proliferation, tumor cell survival, and tumorigenesis in vivo are promoted by the activation of Notch signaling through several isoforms of hairy and enhancer of split 1 (HES1) found in different cellular contexts." (PMID 40149274, 2025). "It is noteworthy that Hes1 knockout mice exhibited more significant suppression of tumor growth following treatment with combined immune checkpoint inhibitors, such as anti-PD-1 antibodies, further highlighting the potential of Hes1 as a synergistic target in immunotherapy." (PMID 40755759, 2025). "This correlation was not evident in tumors treated with the vehicle alone, confirming that HES1 might be a predictive biomarker of efficacy and plays a relevant role in the mechanism of 2OHOA to induce tumor shrinkage in those that respond to this treatment." (PMID 39400678, 2025). "Notably, the expression level of Hes1 is significantly correlated with tumor clinical stage, prognosis, and drug resistance." (PMID 40755759, 2025). "Additionally, we found that corticosterone inhibits GSK3β activity, which led to the upregulation of key Notch signaling pathway members (NICD and HES1) in OC cells, thus facilitating tumor progression and metastasis." (PMID 41488655, 2025). "Future research should further elucidate: 1) the signal regulation network of Hes1 in different tumor microenvironment; 2) the molecular switching mechanism underlying its stage-dependent role; and 3) the synergistic mode of action with driver genes such as KRAS." (PMID 40755759, 2025). "Other findings reflective of CS1’s higher tumor grade and more aggressive behavior compared with CDS11 cells include the significantly higher mRNA levels of INSULINR, IGF2R, IRS1, NOTCH1, JAGGED1, HES1, and HIF1α, which function to promote tumor cell growth and survival." (PMID 40427168, 2025). "We also assessed whether NOTCH1 and HES1 could play a role in tumor progression and metastasis through EMT induction." (PMID 41009728, 2025). "Additionally, Hes1 regulates the tumor microenvironment and immune cell activity, further influencing tumor progression." (PMID 40755759, 2025). "This implies that in the context of high Hes1 expression, the progression of the cell cycle may be accelerated, promoting continuous proliferation of tumor cells and thus fueling tumor development." (PMID 40755759, 2025). "HES1 expression was also successfully evaluated in 163 out of 165 tumor samples." (PMID 41009728, 2025). "In addition, we observed a discordant degree of expression between NOTCH1 and HES1 in the same tumor samples." (PMID 40387567, 2025). "As this conditional Hes1 KO using LysM deletes Hes1 not only in macrophages but also in other myeloid lineages, including monocytes, neutrophils, and DCs, we identified the specific myeloid cell type responsible for reduced tumor growth." (PMID 39702544, 2024). "Similarly, depletion of CD8+ T cells using antibodies resulted in a complete reversal of the anti-tumor effect of Hes1-cKO." (PMID 39702544, 2024). "These are reasonable to explain why HES1, a regulator in the differentiation decision of hemato‐endothelial fate, showed minimal expression specifically in lymphocytes but was highly expressed in tumour cells, fibroblasts, and especially endothelial cells." (PMID 39210544, 2024). "We found that various tumor-promoting cytokines increased Hes1 expression." (PMID 39702544, 2024). "With integrative analysis of whole genome CRISPR screening data from DepMap Project, GBC RNAseq data, and the Coltron prediction results, five CRC TFs (SOX9, TCF7L2, FOXA1, TGIF1 and HES1) were found to meet all our defined criteria for gene expression and tumor‐dependency levels." (PMID 39492805, 2024). "Thus, HES1 expression is upregulated in response to tumor-derived soluble factors or anti-inflammatory stimuli and this phenotype is regulated by the Notch signaling pathway." (PMID 39702544, 2024). "Hes1 deletion also resulted in a significant reduction in tumor weight." (PMID 39702544, 2024).
tumor (continued). "Interestingly, among tumor tissue-infiltrating immune cells, reduced Hes1 expression was also observed in DCs, as well as in neutrophils and macrophages." (PMID 39702544, 2024). "Notably, numbers of ARG1-positive immune cells were significantly reduced by the Hes1 KO, with a decrease in the numbers of tumor-promoting TAMs that were CD163-positive macrophages." (PMID 39702544, 2024). "Hes1 deletion resulted in substantially reduced tumor growth compared with that in the WT mice." (PMID 39702544, 2024). "The loss of HES1, a canonical Notch signaling target, may cooperate with KRAS mutations to remodel the extracellular matrix and to suppress the anti-tumor immune response." (PMID 36824959, 2023). "Furthermore, we performed phenotypic rescue experiments to prove that overexpression of HES1-FLAG in SOX1-expressing H1299 cells partly reversed the tumor-suppressive effect." (PMID 37190139, 2023). "Our results suggest that SOX1 might perform its tumor-suppressive function by inhibiting the expression of HES1." (PMID 37190139, 2023). "Results from NanoString analysis showed positive correlation between HES1-loss and tumor migration and invasion but negative correlation with tumor proliferation." (PMID 37749297, 2023). "Although a number of studies have demonstrated that HES1 functioned as an oncogene in CRC by promoting tumor proliferation and metastasis, the molecular mechanisms underlying the pro-tumor effects of HES1 are largely unknown." (PMID 37957183, 2023). "Nevertheless, these findings support a vital role of M2 macrophage polarization and a role of IL10 and IL6/STAT3 signaling in HES1 (−) KRAS mutant CRCs that may act in concert to promote tumor progression and metastasis." (PMID 37749297, 2023). "Our results provide a proof of concept and suggest that SOX1 might perform its tumor-suppressive function by inhibiting the expression of HES1." (PMID 37190139, 2023). "The results showed that HES1 was highly expressed in CRC tumor tissues." (PMID 37957183, 2023). "Inhibition of FAO by overexpressing HES1 alleviated SIRT3-induced chemoresistance in AML, suggesting that HES1 may be one of the key tumor suppressors outside the mitochondria targeted by SIRT3." (PMID 35955415, 2022). "The fact that the genetic depletion of HES1 had a greater impact on tumor size compared to JI130 might also mean that this particular agent will not be able to fully inhibit HES1 to the extent needed due to toxicity." (PMID 36037042, 2022). "While Notch blockade in a tumour’s endothelium results in reduced NO levels, it has been reported that Notch overactivity negatively regulates NO levels in healthy hepatic sinusoidal endothelial cells, possibly due to the control of Hes1 or Hey1." (PMID 35954226, 2022). "Loss of RBP-J did not affect overall tumor burden but led to a significant reduction in HES1+ and CC10+ cells in the tumors." (PMID 35577801, 2022). "However, in vivo in SMS‐CTR tumor xenografts, YAP1 suppression was associated with a decline in HES1." (PMID 36037042, 2022). "Moreover, Hes1 overexpression was associated with an increased matrix metalloproteinases members (MMP2 and MMP9) mRNA levels in CRC cells, promoting tumor invasion." (PMID 36229883, 2022). "PAUPAR serves as tumor suppressor in uveal melanoma via negatively regulation of Hes1 expression." (PMID 36229883, 2022). "Moreover, Notch-induced Hes1 was suggested to control the expansion of an undifferentiated precursor cell population, thereby promoting Kras-mediated tumor initiation and progression." (PMID 34888306, 2021). "Western blotting confirmed that DBZ reduced the levels of the active NOTCH1 (cleaved NOTCH1) and its target HES1 protein and that Erlotinib lowered the EGFR phosphorylation level in H3118 xenografts, suggesting that tumor suppression was caused by on-target effects of each drug." (PMID 33473104, 2021).